NR1H2 (nuclear receptor subfamily 1 group H member 2)
Description:
Nuclear receptor that exhibits a ligand-dependent transcriptional activation activity. Binds preferentially to double-stranded oligonucleotide direct repeats having the consensus half-site sequence 5'-AGGTCA-3' and 4-nt spacing (DR-4). Interplays functionally with RORA for the regulation of genes involved in liver metabolism (By similarity). Induces LPCAT3-dependent phospholipid remodeling in endoplasmic reticulum (ER) membranes of hepatocytes, driving SREBF1 processing and lipogenesis (By similarity). Via LPCAT3, triggers the incorporation of arachidonate into phosphatidylcholines of ER membranes, increasing membrane dynamics and enabling triacylglycerols transfer to nascent very low-density lipoprotein (VLDL) particles (By similarity). Via LPCAT3 also counteracts lipid-induced ER stress response and inflammation, likely by modulating SRC kinase membrane compartmentalization and limiting the synthesis of lipid inflammatory mediators (By similarity). Plays an anti-inflammatory role during the hepatic acute phase response by acting as a corepressor: inhibits the hepatic acute phase response by preventing dissociation of the N-Cor corepressor complex.
Synonyms: LXRB; NER; UNR; NER-I; RIP15; LXR-b
Tractability: Small molecule: a drug acting on it is in phase 2 or 3 trials; a structure with a bound ligand is known; a high-quality ligand is known; it has a high-quality binding pocket; it belongs to a druggable protein family. PROTAC: UniProt records ubiquitination sites on it; ubiquitination databases record sites on it; a small molecule that binds it is known.
Target class: Nuclear hormone receptor subfamily 1 group H member 3; Nuclear receptor; Nuclear hormone receptor subfamily 1 group H; Nuclear hormone receptor subfamily 1; Transcription factor
Chemical probes: GSK2033, GW-3965 (high quality), LXR-623 (high quality), PD082590, PD082955, PD084204, SR9238, SR9243 (high quality), TO-901317 (high quality)
Safety:
Unwanted effects reported when the protein is acted on. In parentheses: how it was acted on, where the effect was seen, and who reports it.
Increased, Liver Steatosis (activation; source: AOP-Wiki)
N/A, Liver Steatosis (activation; source: AOP-Wiki)
diarrhea (source: ClinPGx)
Gene: Protein-coding gene on chromosome 19 (50,329,640 to 50,383,404, forward strand). Ensembl gene ENSG00000131408.
Subcellular location: Nucleus
Subcellular location (Human Protein Atlas): Nucleoplasm; Vesicles
Pathways (Reactome):
Signal Transduction: NR1H2 & NR1H3 regulate gene expression linked to lipogenesis; NR1H2 & NR1H3 regulate gene expression linked to triglyceride lipolysis in adipose; NR1H2 & NR1H3 regulate gene expression to control bile acid homeostasis; NR1H2 & NR1H3 regulate gene expression to limit cholesterol uptake; NR1H3 & NR1H2 regulate gene expression linked to cholesterol transport and efflux
Gene expression (Transcription): Nuclear Receptor transcription pathway
Metabolism: PPARA activates gene expression
Metabolism of proteins: SUMOylation of intracellular receptors
Transport of small molecules: VLDLR internalisation and degradation
Gene Ontology:
Molecular function: apolipoprotein A-I receptor binding; ATPase binding; DNA-binding transcription activator activity, RNA polymerase II-specific; protein binding; RNA polymerase II cis-regulatory region sequence-specific DNA binding; DNA binding; DNA-binding transcription factor activity, RNA polymerase II-specific; nuclear receptor activity; DNA-binding transcription factor activity; nuclear retinoid X receptor binding; sequence-specific DNA binding; zinc ion binding
Biological process: negative regulation of cholesterol storage; negative regulation of DNA-templated transcription; negative regulation of lipid transport; negative regulation of pinocytosis; positive regulation of cholesterol efflux; positive regulation of cholesterol transport; positive regulation of DNA-templated transcription; positive regulation of fatty acid biosynthetic process; positive regulation of transcription by RNA polymerase II; positive regulation of triglyceride biosynthetic process; cell differentiation; cholesterol homeostasis; hormone-mediated signaling pathway; intracellular receptor signaling pathway; mRNA transcription by RNA polymerase II; negative regulation of cold-induced thermogenesis; negative regulation of inflammatory response; negative regulation of macrophage derived foam cell differentiation; negative regulation of response to endoplasmic reticulum stress; negative regulation of transcription by RNA polymerase II; negative regulation of type II interferon-mediated signaling pathway; phosphatidylcholine acyl-chain remodeling; regulation of lipid storage; lipid metabolic process; negative regulation of gene expression; and 4 more
Cellular component: cytoplasm; nucleoplasm; nucleus; RNA polymerase II transcription regulator complex; chromatin; cytosol
Genetic constraint (gnomAD): Loss-of-function variants: 31 observed, 46.44 expected, observed/expected ratio (o/e) 0.67, 90% interval 0.5 to 0.9. The upper end of that interval is the gene's LOEUF score, 0.9, which puts it in group 3 of 6, group 1 being the genes least tolerant of losing a copy. Missense variants: 589 observed, 627.74 expected, observed/expected ratio (o/e) 0.94, 90% interval 0.88 to 1. Synonymous variants: 310 observed, 258.54 expected, observed/expected ratio (o/e) 1.2, 90% interval 1.09 to 1.32.
Homologues: Orthologues: chimpanzee NR1H2 (100% identical), macaque NR1H2 (99% identical), dog NR1H2 (94% identical), guinea pig NR1H2 (92% identical), pig NR1H2 (91% identical), rat Nr1h2 (88% identical), mouse Nr1h2 (87% identical), tropical clawed frog nr1h2 (71% identical), Drosophila melanogaster EcR (33% identical), Caenorhabditis elegans sex-1 (22% identical), Caenorhabditis elegans nhr-23 (20% identical), Caenorhabditis elegans nhr-114 (18% identical), and 181 more. Paralogues in human: NR1H3 (61% identical), NR1H4 (32% identical), VDR (26% identical), NR1I2 (25% identical), RARG (25% identical), RARA (25% identical), NR1D2 (25% identical), RARB (24% identical), NR1I3 (24% identical), NR1D1 (24% identical), THRB (23% identical), PPARD (23% identical), and 6 more.
Diseases named in the same sentence as NR1H2 in open-access papers:
NR1H2 is named in the same sentence as 69 diseases in open-access papers, as found by Europe PMC text mining. Sharing a sentence is not in itself a finding about the gene and the disease. The quoted sentences say what the papers report.
colorectal cancer (7 papers, 2003 to 2023). A primary or metastatic malignant neoplasm that affects the colon or rectum. "NR1H2 suppresses inflammatory genes in macrophages (A-González NCastrillo, 2011), activates liver X receptors, and inhibits cancer cell growth, including colorectal cancer." (PMID 37745301, 2023). "Nevertheless, activation of NR1H2 which falls in to liver X receptors was shown to inhibit proliferation of HT29 colorectal cancer cells." (PMID 29065888, 2017). "To uncover the regulatory role of NR1H2 and SNAI1 in colorectal cancer, we also performed DAVID functional enrichment analysis of the sets of their target genes inferred by miRGTF-net." (PMID 34938324, 2021).
Alzheimer disease (6 papers, 2019 to 2025). A progressive, neurodegenerative disease characterized by loss of function and death of nerve cells in several areas of the brain leading to loss of cognitive function such as memory and language. "The NR1H2 gene encodes liver X receptor beta and has been linked to cognitive impairments in Alzheimer's disease, partly through affecting Aß accumulation and cholesterol homeostasis." (PMID 40046430, 2024). "When underexpressed, NR1H2 increases cellular cholesterol ­levels and amyloidogenesis by downregulating the apolipoprotein E.14Specifically, the T allele of rs2695121 (NR1H2) may affect the risk of Alzheimer’s disease and produce higher behavioral burden." (PMID 40834163, 2025). "Moreover, the genetic variability at NR1H2 may contribute to an increased risk of Alzheimer’s disease, and the preeclampsia was associated with a polymorphism in NR1H2." (PMID 31149403, 2019).
breast carcinoma (5 papers, 2016 to 2021). "In the liver, NR1H2/NR1H3 stimulation results in sulfotransferase (an enzyme critical for estrogen deactivation) induction which inhibits breast-cancer growth in xenografted mice." (PMID 26894976, 2016). "In mouse breast-cancer models, 27-hydroxycholesterol augments ER-dependent mammary-tumor growth and increases NR1H2/NR1H3-dependent metastasis." (PMID 26894976, 2016). "The data obtained in these mouse models contrast with the observations made in some breast-cancer cells, where NR1H2/NR1H3 activation reduces proliferation with down-regulation of genes involved in cell cycle progression, DNA replication and other cell-growth-related processes." (PMID 26894976, 2016). "In conclusion, NR1H2/NR1H3 activation may represent a strategy for the treatment/chemoprevention of breast-cancer, although caution should be exercised, since NR1H2/NR1H3-agonists may favor the metastatic spread of tumor cells." (PMID 26894976, 2016). "On the basis of our analysis, we conclude that the Lipid-Sensors, NR1C3, NR1H2 and NR1H3 are likely to be onco-suppressors in breast-cancer." (PMID 26894976, 2016). "As for the potential role of NR1H2 and NR1H3 in breast-cancer, little and contrasting evidence is available." (PMID 26894976, 2016). "Among these, 34 hotspot mutations such as CD209 R129 missense (4.0 %) in bladder cancer, MAGI1 Q421 insertion (0.8 %) and NR1H2 Q175 insertion (1.8 %) in breast cancer were not well investigated based on previous studies and are potentially novel targets." (PMID 27356755, 2016).
melanoma (5 papers, 2015 to 2021). A malignant, usually aggressive tumor composed of atypical, neoplastic melanocytes. "Agonist activation of the Liver X Receptor Beta isoform (NR1H2) has been shown to suppress the growth and metastasis of melanoma cells by transcriptional induction of apolipoprotein-E86." (PMID 31019223, 2019).
lung carcinoma (4 papers, 2007 to 2025). "Liver X receptor (NR1H2/3) agonists inhibited proliferation of A549 lung cancer cells and HT29 colorectal adenocarcinoma cells and markedly enhanced cell death in these cells." (PMID 38890295, 2024).
glioma (3 papers, 2019 to 2023). A benign or malignant brain and spinal cord tumor that arises from glial cells (astrocytes, oligodendrocytes, ependymal cells). "We therefore generated glioma neurosphere lines with CRISPR-mediated knockdown of NR1H2." (PMID 31664073, 2019). "To determine which LXR paralog was likely to be activating ABCA1 in our glioma cells, we used the UCSC Xena browser to look at expression levels of NR1H2 and NR1H3 in normal tissues in the Genotype-Tissue Expression (GTEx) data set." (PMID 31664073, 2019).
Obesity (3 papers, 2009 to 2016). Accumulation of substantial excess body fat. "Polymorphisms in the NR1H2 gene encoding LXRβ mainly associated with obesity and type 2 diabetes." (PMID 26611207, 2016).
preeclampsia (3 papers, 2011 to 2022). Preeclampsia is a hypertensive disorder of pregnancy that is characterized by new-onset hypertension with proteinuria presenting after 20 weeks of gestation, and depending on mild or severe forms may initially present with severe headache, visual disturbances, and hyperreflexia. "Despite the demonstration of an interesting association between the r2695121 polymorphism in NR1H2 (LXRbeta) and preeclampsia, this study was subject to several limitations." (PMID 22029530, 2011). "We assessed associations between single nucleotide polymorphisms of NR1H3 (rs2279238 and rs7120118) and NR1H2 (rs35463555 and rs2695121) and the disease in 155 individuals with preeclampsia and 305 controls." (PMID 22029530, 2011). "In conclusion, we demonstrate here, for the first time, an association between a polymorphism of the NR1H2 (LXRbeta) gene and preeclampsia." (PMID 22029530, 2011). "Univariate logistic regression analysis showed that both the SNPs within the NR1H2 gene tested were associated with preeclampsia." (PMID 22029530, 2011). "The two haplotypes of the NR1H2 gene (GT and AC) were associated with preeclampsia (p = 0.009 and p = 0.026, respectively)." (PMID 22029530, 2011). "We report here a new genetic association between the SNP rs2695121, in the NR1H2 gene, and preeclampsia." (PMID 22029530, 2011). "The NR1H2 SNP rs2695121 (NM_007121.4:c.-19-103T > C), which was found to be associated with preeclampsia, is an intronic polymorphism that would therefore also be unlikely to affect protein function." (PMID 22029530, 2011). "This is the first study to investigate the association of the NR1H2 (LXRbeta) gene with preeclampsia." (PMID 22029530, 2011). "This study provides the first evidence of an association between the NR1H2 gene and preeclampsia, adding to our understanding of the links between cholesterol metabolism and this disease." (PMID 22029530, 2011). "The aim of this study was to investigate associations between the NR1H3 and NR1H2 genes and preeclampsia." (PMID 22029530, 2011). "Our work reveals that the NR1H2 (LXRbeta) SNP rs2695121 is a risk factor for preeclampsia." (PMID 22029530, 2011). "Interestingly, both NR1H2 (LXRbeta) SNPs (rs35463555 and rs2695121) were found to be significantly associated with preeclampsia, which was more frequent in individuals homozygous for the mutated alleles." (PMID 22029530, 2011). "A deeper replication study, including a larger number of polymorphisms, may facilitate definition of the contribution of NR1H2 to the pathogenesis of preeclampsia." (PMID 22029530, 2011). "These predictions suggest that the positive association between the NR1H2 rs2695121 SNP and preeclampsia may result from an indirect association rather than a direct effect of the polymorphism on protein function." (PMID 22029530, 2011). "One recent study revealed that the expression of NR1H3, NR1H2 and their target gene ABCA1 in JAR cells is stimulated under conditions of low oxygen concentration, mimicking the conditions occurring in preeclampsia." (PMID 22029530, 2011).
type 2 diabetes mellitus (3 papers, 2011 to 2024). A type of diabetes mellitus that is characterized by insulin resistance or desensitization and increased blood glucose levels. "The obtained results indicate that the increased NR1H2 expression in the aging liver may be one of the key effects involved in the resistance to the development of type 2 diabetes." (PMID 31149403, 2019). "The NR1H2 encoding liver X receptor (LXR)-β was found to be universally expressed, and the variation within the NR1H2 gene may facilitate the development of type 2 diabetes." (PMID 31149403, 2019). "Furthermore, the variation within the NR1H2 gene may facilitate the development of type 2 diabetes." (PMID 31149403, 2019).
atherosclerosis (2 papers, 2017 to 2023). A disease characterized by the build-up of fatty material and calcium deposition in the arterial wall resulting in partial or complete occlusion of the arterial lumen. "Up-regulated DEGs included known atherosclerosis genes such as the liver X receptor gene NR1H2, and NEXN, TRAF1, TLR7 and LGALS3BP, implicating tumor necrosis factor and toll-like receptor signaling and glycan-binding protein pathways." (PMID 37205656, 2023).
breast tumors (2 papers, 2019 to 2021). "To test this, we examined whether expression of NR1H3/LXRA or NR1H2/LXRB correlated with expression of canonical LXR target genes (ABCA1 and APOE) in 81 ER-negative or 234 ER-positive primary breast tumours (obtained from TCGA dataset)." (PMID 31683867, 2019).
Cognitive impairment (2 papers, 2023 to 2024). Abnormal cognition is characterized by deficits in thinking, reasoning, or remembering. "Association studies examining the NR1H2 gene in AD patients seem to be in line with our findings, as the rs1405655 C-allele was shown to segregate in families with this cognitive impairment." (PMID 36675784, 2023).
colitis (2 papers, 2022). Inflammation of the colon. "By comparing colonic mRNA levels of various BARs in colitis animals, most BARs levels were increased in PCDSS mice, such as Gpbar1(TGR5), Vdr, Nr1h3 (LXRα), Nr1h2 (LXRβ), Nr1i2 (PXR), and Nr1i3 (CAR)." (PMID 36050867, 2022).
COVID-19 (2 papers, 2023). A disease caused by infection with severe acute respiratory syndrome coronavirus 2. "In addition, alleles linked to the downregulation of the NR1H2 gene and impaired cholesterol homeostasis were found to contribute to the manifestation of neurological symptoms during mild-to-moderate COVID-19 illness." (PMID 36675784, 2023). "Another statistically significant result was obtained for rs1405655 residing in the NR1H2 gene, where the rs1405655 C-allele was related to an increased risk of manifesting neurological symptoms during COVID-19 illness in a dose-dependent manner (β = 2.37, p = 0.017, OR = 1.55, 95% CI 1.08–2.23)." (PMID 36675784, 2023).
cutaneous melanoma (2 papers, 2019 to 2024). A primary melanoma arising from atypical melanocytes in the skin. "Activation of the LXR Beta isoform (NR1H2) was shown to inhibit human and murine cutaneous melanoma cell migration in vitro and murine cutaneous melanoma cell metastasis in a mouse xenograft model." (PMID 31019223, 2019).
diabetes (2 papers, 2011 to 2024). "According to the literature, only the INHA and NR1H2 genes are involved in steroidogenesis, sex development, and/or reproduction, while the other genes are either involved in diabetes or cancer." (PMID 39337600, 2024).
glioblastoma (2 papers, 2019 to 2022). The most malignant astrocytic tumor (WHO grade IV). "A dissection of the relationship between NR1H2 and ABCA1 gene expression in the TCGA Glioblastoma data set shows that only very weak correlation, which is in congruence with our experimental findings." (PMID 31664073, 2019). "To address this, we first looked at NR1H2 and ABCA1 gene expression in the TCGA Glioblastoma data set and saw that they are only very weakly correlated." (PMID 31664073, 2019).
osteosarcoma (2 papers, 2013 to 2022). A usually aggressive malignant bone-forming mesenchymal neoplasm, predominantly affecting adolescents and young adults. "In “Pericyte”, differentially expressed NRs such as NR4A1, NR3C1, NR2F2, NR2F1, NR1H2, and ROR were detected among metastasis, primary, and recurrent osteosarcoma tissues." (PMID 35965537, 2022).
Anxiety (1 paper, 2023). Intense feelings of nervousness, tension, or panic often arise in response to interpersonal stresses. "Pyramidal neurons in layer V of the medial prefrontal cortex (mPFC) are primarily involved in mood behaviors, where astrocytic NR1H2 (LXRBB) is critical for synaptic transmission and thus is a potential therapeutic target for the treatment of mood disorders and anxiety-like behavior." (PMID 37363320, 2023).
autism (1 paper, 2024). Persistent deficits in social interaction and communication and interaction as well as a markedly restricted repertoire of activity and interest as well as repetitive patterns of behavior. "This study is the first to explore the potential link between autism and rs2695121/rs17373080 single nucleotide polymorphisms (SNPs) in the regulatory regions of NR1H2, known for their association with neuropsychiatric functions." (PMID 38790546, 2024).
Azoospermia (1 paper, 2024). Absence of any measurable level of sperm,whereby spermatozoa cannot be observed even after centrifugation of the semen pellet. "Similarly, lower expression levels of NR1H2 were detected in the testis of infertile men with azoospermia." (PMID 39337600, 2024).